DNMT3A (DNA methyltransferase 3 alpha)
Diseases named in the same sentence as DNMT3A in open-access papers (continued):
Sharing a sentence is not in itself a finding about the gene and the disease.
chronic lymphocytic leukemia (6 papers, 2016 to 2024). "Dnmt3a inactivation in hematopoietic stem cells has been shown to drive B cell-related malignancies, including chronic lymphocytic leukemia, and associates with specific DNA methylation patterns in transformed cells." (PMID 29326230, 2018). "Conditional and B cell-specific deletion of Dnmt3a causes chronic lymphocytic leukemia and the immunization of B cells deficient for Dnmt3a and Dnmt3b resulted in the antigen-specific expansion of B cells in germinal centers, plasma cell accumulation, and elevated levels of serum antibodies." (PMID 39123361, 2024). "We have previously shown that inactivation of Dnmt3a in hematopoietic cells results in chronic lymphocytic leukemia in mice." (PMID 27690235, 2016). "Using this model, we previously showed that long-term Dnmt3a-defficiency resulted in the development of a chronic lymphocytic leukemia (CLL) around 1 year of age." (PMID 27690235, 2016). "For instance, along with DNMT3A, DNMT3B belongs to the top 1% of underexpressed genes in human chronic lymphocytic leukemia (CLL)." (PMID 33450231, 2021).
colitis (6 papers, 2022 to 2024). Inflammation of the colon. "Research has shown that the 5mC regulatory factor DNMT3A plays a crucial role in colitis-associated cancer, with low expression being favorable for patient prognosis." (PMID 38999959, 2024). "Loss of functional DNMT3A in IECs leads to increased susceptibility to experimental colitis, which suggests a mechanism for how genetic variants in the DNMT3A locus could precipitate into the manifestation of Crohn ́s disease." (PMID 36271073, 2022). "In the present study, we explored the effect and underlying mechanism of DNMT3a in colitis." (PMID 35574272, 2022). "In conclusion, our data showed that DNMT3a was upregulated in DSS-induced colitis mice along with the increased DNA methylation level and proinflammatory cytokines in the colon." (PMID 35574272, 2022). "Based on this experiment, where we observed a delay in body weight gain during the first recovery phase (day 5–10), we hypothesized that DNMT3A plays a critical role during the respective post-colitis recovery phases." (PMID 36271073, 2022). "Mechanistically, DNMT3A deficiency leads to hypomethylation, which impairs the function and regeneration of the intestinal epithelial barrier, making mice more susceptible to DSS-induced colitis, implying a role for impaired epithelial DNMT3A function in the etiology of IBD." (PMID 36590401, 2022).
esophageal cancer (6 papers, 2010 to 2023). A primary or metastatic malignant neoplasm involving the esophagus. "It was found that RAR-β2 promoter hypermethylation was induced by BPDE, and then its expression was decreased by recruiting DNMT3A in combination with RAR-β2, which promoted the occurrence and development of esophageal cancer." (PMID 37391844, 2023). "In a study on esophageal cancer cells, BPDE was found to suppress Rarβ expression via promoter hypermethylation by recruiting DNMT3A." (PMID 23596512, 2013).
Hypertension (6 papers, 2019 to 2024). The presence of chronic increased pressure in the systemic arterial system. "However, it is unclear why ASXL1 is associated with essential hypertension and CHIP DNMT3A mutations have been associated with hypertension in human patients and mice." (PMID 37059828, 2023). "In contrast, anti-Dnmt3a alone did not manage hypertension as effectively as the combined treatment of anti-Dnmt3a and anti-Tet3." (PMID 39595187, 2024).
osteoarthritis (6 papers, 2017 to 2024). A noninflammatory degenerative joint disease occurring chiefly in older persons, characterized by degeneration of the articular cartilage, hypertrophy of bone at the margins and changes in the synovial membrane. "In individuals suffering from degenerative arthritis, the functionality of the IL-6 gene is associated with DNMT3A expression, and those with increased DNMT3A expression exhibit significantly lower levels of IL-6 secretion." (PMID 37626784, 2023). "In patients with osteoarthritis, IL-6 gene activity is associated with the expression of DNMT3A and significantly lower levels of IL-6 secretion are found in those with DNMT3A overexpression." (PMID 33861346, 2021). "The aim of this research is to explore the effect of miR‐200b‐3p targeting DNMT3A on the proliferation and apoptosis of osteoarthritis (OA) cartilage cells." (PMID 28345813, 2017). "Such as has_circ_0136474, which regulates IL-1β-Induced chondrocyte injury through miR-766-3p/DNMT3A Signaling Pathway; Circ-BRWD1, which contributes to osteoarthritis development through the modulation of miR-1277/TRAF6 axis." (PMID 34652255, 2021).
systemic sclerosis (6 papers, 2022 to 2025). A chronic disorder, possibly autoimmune, marked by excessive production of collagen which results in hardening and thickening of body tissues. "However, CHIP has been significantly associated with systemic sclerosis in patients under 50 years of age, with DNMT3A being the most frequently mutated gene." (PMID 37947606, 2023). "The DNMT3A-induced silencing of SOCS3 expression stimulates TGF-β-dependent fibroblast activation in experimental systemic sclerosis (SSc) murine models." (PMID 37189665, 2023). "Once again, most mutations occurred in the DNMT3A gene, suggesting a potential connection between DNMT3A-driven CHIP and both SLE and systemic sclerosis." (PMID 37947606, 2023). "DNMT3A was found to be hypermethylated and underexpressed in systemic sclerosis microvascular endothelial cells, whereas CTNNA1 was found to be hypomethylated." (PMID 37039566, 2023). "Furthermore, epigenetic dysregulation of both DNMT3A and SELPG is associated with systemic sclerosis." (PMID 37039566, 2023). "Only one study revealed that the intravenous injections of ASCs EVs could effectively slow-down the course of the systemic sclerosis via regulating miR-29a-3p/Dnmt3a/Pdgfrbb/Bcl2/Bcl-xl axis." (PMID 35505389, 2022). "In terms of epigenetic modulators, the increased expression of DNA methyltransferases 3A and 1 (DNMT3A and DNMT1) was observed in TGFβ–activated fibroblasts from fibrotic skin patients with systemic sclerosis (SSc), a prototypical idiopathic fibrotic disease." (PMID 37569677, 2023). "For instance, systemic sclerosis (SSc) patients show a higher prevalence of CHIP (25%) compared to healthy individuals (4%), with DNMT3A mutations being most common, although no significant clinical differences were noted between CHIP and non-CHIP carriers." (PMID 39997650, 2025).
thrombosis (6 papers, 2021 to 2025). "Age greater than 60 years, the presence of the cardiovascular risk factors, mutation for thrombosis (DNMT3A, ASXL1, or BCOR/BCORL1), and previous thrombosis made part of this score." (PMID 41153823, 2025). "Further, the presence of ≥1 CHIP driver mutation (in DNMT3A, TET2, or ASXL1) significantly increased the risk of thrombosis in patients with polycythemia vera." (PMID 37947606, 2023). "Among patients with variations associated with CHIP (DNMT3A, TET2, ASXL1, JAK2), thrombosis occurred in 5 patients (62%; odds ratio [OR], 5.6; 95% CI, 1.3-15.9) and death in 3 patients (37%; OR, 6.1; 95% CI, 1.3-26.9)." (PMID 34357393, 2021). "This indicates a novel DNMT3A-mediated pathway that may be activated to promote lower extremity deep vein thrombosis." (PMID 37947606, 2023). "Recently, Zhang and Qin demonstrated that in patients with lower extremity deep vein thrombosis, lncRNA LINC00659 facilitated the DNMT3A-mediated methylation of the fibroblast growth factor 1 (FGF1) promotor, which inhibited the proliferation and angiogenesis ability of endothelial progenitor cells." (PMID 37947606, 2023).
acute monocytic leukemia (5 papers, 2018 to 2022). Acute monoblastic leukemia (AML-M5), is one of the most common subtypes of acute myeloid leukemia (AML) that is either comprised of more than 80% of monoblasts (AML-M5a) or 30-80% monoblasts with (pro)monocytic differentiation (AML-M5b). "Researchers have pointed out that AML patients with a DNMT3A mutation tend to be M4/M5 subtype, and therefore, we have also chosen the human acute monocytic leukemia cell line, THP1, for our studies." (PMID 36303144, 2022). "Somatic mutations in DNMT3A and its reduced enzymatic activity have been observed in acute monocytic leukemia." (PMID 36618443, 2021). "For instance, acute monocytic leukemias frequently (20.5%) carry mutations in the de novo DNA methyltransferase gene DNMT3A, displaying aberrant genome-wide DNA methylation profiles." (PMID 30897760, 2019). "A 22-year-old male was diagnosed with acute monocytic leukemia with FLT3-ITD and DNMT3A mutations and pulmonary infection." (PMID 29843647, 2018). "Therefore, in this article, we present a rare case of HLH that occurred at the stage of induction chemotherapy in a patient with acute monocytic leukemia with FLT3-ITD and DNMT3A mutations." (PMID 29843647, 2018). "Therefore, he was clinically diagnosed with acute monocytic leukemia with FLT3-ITD and DNMT3A mutations and pulmonary infection." (PMID 29843647, 2018).
acute promyelocytic leukemia (5 papers, 2011 to 2025). An aggressive form of acute myeloid leukemia (AML), characterized by arrest of leukocyte differentiation at the promyelocyte stage, due to a specific chromosomal translocation t(15;17) in myeloid cells. "To assess their prognostic significance, we determined the mutational status of DNMT3A exon 23 in 288 patients with AML excluding acute promyelocytic leukemia, aged from 18 to 65 years and treated in Toulouse University Hospital." (PMID 22081665, 2011). "Di Croce found that PML-RAR fusion protein, an oncogenic transcription factor, recruited DNMT1 and DNMT3A to retinoic acid receptor beta 2 leading to its methylation and subsequent gene silencing in acute promyelocytic leukemia (APL)." (PMID 38696033, 2024).
atrial fibrillation (5 papers, 2023 to 2026). A disorder characterized by an electrocardiographic finding of a supraventricular arrhythmia characterized by the replacement of consistent P waves by rapid oscillations or fibrillatory waves that vary in size, shape and timing and are accompanied by an irregular ventricular response. "In contrast, JAK2-CHIP exhibited inverse associations with intracerebral hemorrhage and atrial fibrillation, whereas DNMT3A-CHIP was positively associated with atrial fibrillation and inversely associated with abdominal aortic aneurysm." (PMID 42131836, 2026). "The calcium signaling pathway and ECM-receptor interaction, which are genetically associated with the progression and recurrence of atrial fibrillation, and the Hippo signaling pathway were up-regulated in DNMT3A KO cells (FDR p values were 0.002449, 0.004114, and 0.03080, respectively)." (PMID 41450820, 2025). "CHIP associated with DNMT3A and TET2 mutations has recently been associated with an enrichment of pro-inflammatory cardiac monocyte-derived macrophages and an increased risk of post-operative atrial fibrillation in patients." (PMID 37947606, 2023). "In patients with recurrent atrial fibrillation, serum levels of DNMT3A and phosphatidylinositol 3-kinase (PI3K) and Akt/Protein Kinase (PI3K-Akt) were positively correlated with the left atrial volumes, while miR-200b was negatively correlated with the left atrial volume." (PMID 37947606, 2023). "miR-200b levels were also negatively correlated with DNMT3A and PI3K-Akt protein levels, suggesting that DNMT3A may contribute to recurrent atrial fibrillation by downregulating miR-200b and thereby activating PI3K-Akt." (PMID 37947606, 2023).
autism spectrum disorder (5 papers, 2017 to 2025). A spectrum of developmental disorders that includes autism, and Asperger syndrome. "Notably, disruption of DNMT3A has recently been reported as the underlying cause of the neurodevelopmental disorder Tatton–Brown–Rahman syndrome, and mutations in DNMT3A have been identified in individuals diagnosed with autism spectrum disorders." (PMID 29037228, 2017).
chronic myelocytic leukemia (5 papers, 2013 to 2024). "The individual with the DNMT3A p.R693H variant had not had any haematological malignancy prior to death (at age 89 years), while the individual with the SF3B1 p.K666N variant had chronic myeloid leukaemia." (PMID 29641532, 2018).
COVID-19 (5 papers, 2020 to 2023). A disease caused by infection with severe acute respiratory syndrome coronavirus 2. "To dissect the regulatory mechanism of CHIP (+)-specific IFN-γ response gene expression in severe COVID-19, we identified DNMT3A CHIP mutation-dependent differentially methylated regions (DMRs) and annotated their putative target genes based on long-range chromatin interactions." (PMID 36229591, 2022). "In summary, we observed a high frequency of CHIP, mainly involving TET2 and DNMT3A genes, in a cohort of COVID-19 patients." (PMID 36184726, 2023). "DNMT1 and DNMT3A had an inverse correlation with the severity of COVID-19 (r = -0.242 and -0.233, respectively)." (PMID 36840831, 2023). "DNMT3A and TET2 variants were the most frequent, with CHIP affecting 41% (N = 110) and 30% (N = 80) of our cohort of COVID-19 patients, respectively." (PMID 36184726, 2023). "In our study, COVID-19 patients displayed unexpected significant downregulation of DNMT3A and DNMT3B expression." (PMID 36840831, 2023). "Overall, mutations in DNMT3A and/or TET2 were present in 36% (44/122) of COVID-19 patients and were found in 80% (44/55) of those with CH." (PMID 32708264, 2020). "DNMT1 and DNMT3A were negatively correlated with COVID-19 severity." (PMID 36840831, 2023). "Given that CHIP is driven by mutations in multiple epigenetic regulators, such as DNMT3A, TET2, and ASXL1, we hypothesized that altered chromatin activity might play a critical role in facilitating IFN-γ response gene expression in severe COVID-19." (PMID 36229591, 2022). "In this study, we analyzed the expression profile of DNMTs (DNMT1, DNMT3A, DNMT3B) and HDACs (HDAC2 and HDAC3) in COVID-19 patients." (PMID 36840831, 2023). "DNMT1, DNMT3A, and DNMT3B were inversely correlated with COVID-19 (r = -0.215, -0.528, and -0.335, respectively)." (PMID 36840831, 2023). "The study revealed a pattern of decreased expression of DNMT genes (DNMT3A and DNMT3B) and an increase in the methylation of the TNF-α and TLR4 promoters in COVID-19 patients, as well as a correlation between global methylation and disease severity." (PMID 36840831, 2023). "Compared with the healthy COVID-19-free group, the expression of DNMT3A and DNMT3B in the blood of COVID-19 patients was decreased (P = 0.008 and 0.048, respectively)." (PMID 36840831, 2023). "Analysis of an ROC curve identified both DNMT3A and DNMT3B as predictive biomarkers for COVID-19, and their combination increases their predictive power, as indicated by increasing AUC." (PMID 36840831, 2023). "In our study, all DNMTs were inversely correlated with COVID-19 disease, whereas DNMT1 and DNMT3A, but not DNMT3B, had an inverse relationship with disease severity." (PMID 36840831, 2023). "We conducted a case-control study to investigate the differential expression of DNMT1, DNMT3A, DNMT3B, HDAC2, and HDAC3 in the blood of 120 patients (30 mild, 30 moderate, 30 severe, and 30 critical) and 30 healthy subjects without COVID-19." (PMID 36840831, 2023). "In contrast to previous reports, DNMT3A and DNMT3B expression was found to be significantly downregulated in COVID-19 cases, whereas DNMT1, HDAC2, and HDAC3 expression did not change." (PMID 36840831, 2023).
dwarfism (5 papers, 2020 to 2024). "We herein report that substitutions of the aspartic acids in the mouse DNMT3A ADD domain cause dwarfism and female infertility." (PMID 37527244, 2023). "Recent data showed that aberrant DNAme at these developmentally regulated genes was associated with dwarfism in mouse and human with DNMT3A mutations." (PMID 33916664, 2021). "The higher methylation observed in the patient with dwarfism suggests a higher impact of this variant in the activity of DNMT3A." (PMID 33182397, 2020). "We herein show that amino-acid substitutions in the ADD domain of mouse DNMT3A cause dwarfism." (PMID 37527244, 2023). "To explore this, we investigated the methylation status of the 307 differentially methylated probes in lymphocyte DNAs from the previously reported PGL DNMT3A variant carriers and in blood samples from patients with either overgrowth or dwarfism due to DNMT3A germline variants." (PMID 33182397, 2020). "Interestingly, a mutant version of DNMT3A carrying two point mutations within the ADD domain, which interfere with the binding of DNMT3A to H3K4me0 in vitro, was recently shown to lead to dwarfism and female infertility." (PMID 38505259, 2024).
folate deficiency (5 papers, 2017 to 2022). A nutritional condition produced by a deficiency of FOLIC ACID in the diet. "Folate deficiency (BNFD) led to an increase in transcript levels of DNMT3A in the kidney, liver (females) however, with folate over-supplementation (BNFO) expression was increased in the kidney (female) when compared to folate normal (BNFN)." (PMID 31772242, 2019). "B12 over-supplementation, combined with folate deficiency (BOFD) increased the expression of DNMT3A in all tissues whereas in combination to folate normal (BOFN) expression was increased in kidney and placenta compared to BNFN." (PMID 31772242, 2019). "B12 over-supplementation combined with folate normal (BOFN) as well as folate over-supplementation (BOFO) increased the expression of DNMT3A in fetal tissues whereas in combination to folate deficiency (BOFD) expression was increased in female fetal tissues as compared to BNFN." (PMID 31772242, 2019). "Hence, the gestation associated increased global methylation might be due to increased expression of DNMT1 and DNMT3A, and abnormally high DNMTs expression in association with folate deficiency results in the abnormal global methylation in preeclampsia." (PMID 35578613, 2022). "In another study related to folate deficiency, the expression of DNMT1 and DNMT3A were found to be up-regulated in the uteruses of pseudo-pregnant mice." (PMID 31772242, 2019). "Folic acid deficiency further downregulated DNMT1 and DNMT3a mRNA levels in DM mice." (PMID 28422052, 2017). "In comparison to BNFN, folate deficiency combined with either state of B12 (BNFD, BDFD, BOFD) overall led to an increase in DNMT3A levels in all fetal tissues regardless of sex." (PMID 31772242, 2019).
idiopathic pulmonary fibrosis (5 papers, 2018 to 2024). Idiopathic pulmonary fibrosis (IPF) is a nonneoplastic pulmonary disease that is characterized by the formation of scar tissue within the lungs in the absence of any known cause. "Interestingly, inhibition of DNA methylase levels (DNMT1, DNMT3a, and DNMT3b) promotes PPARγ expression and improves pulmonary fibrosis." (PMID 37986543, 2024).
Immunodeficiency (5 papers, 2020 to 2025). Failure of the immune system to protect the body adequately from infection, due to the absence or insufficiency of some component process or substance. "Moreover, reduced expression levels of DNMT3A, METTL3, and YTHDF1 were associated with immune diseases or immune signalling pathways." (PMID 39485681, 2024). "Similarly, exploring the molecular basis of TET2-associated immunodeficiency and TBRS, both of which are strongly linked to increased risk of hematopoietic malignancy, will help to elucidate the roles of TET2 and DNMT3A mutations as drivers of cancer." (PMID 36814905, 2023).